KRT7 (keratin 7)
Diseases named in the same sentence as KRT7 in open-access papers (continued):
Sharing a sentence is not in itself a finding about the gene and the disease.
tumor (continued). "Early hyperplastic tumor cells showed high expression of Krt6 and Krt5, decreased expression of Loricrin (Lor), and a lack of Krt7 expression." (PMID 31110179, 2019). "Immunohistochemical staining revealed that the tumor cells were positive for cytokeratin-7 (CK-7) and Wilms tumor-1 (WT-1) and negative for cytokeratin-20 (CK-20) and estrogen receptor (ER)." (PMID 31222668, 2019). "Immunohistochemical analysis showed that the tumor cells were positive for cytokeratin 7 (CK7) and negative for CK20." (PMID 30031391, 2018). "In our case, tumor cells expressed cytokeratin 5/6 and cytokeratin 7, SMA, S-100 protein, and p63, but they were negative for desmin." (PMID 29489937, 2018). "Notably, all overexpressed keratins, i.e. KRT5A, KRT6A, KRT7, KRT14, KRT17, were found to play a role as LUAD tumor progression determinants." (PMID 30473748, 2018). "Notably, though, all overexpressed keratins, i.e. KRT5A, KRT6A, KRT7, KRT14, KRT17, were found to play a role as LUAD tumor progression determinants." (PMID 30473748, 2018). "A minority of tumours originated from the colorectal zone of the anal canal were negative for Krt20 (4/48, 8.3%) or displayed a patchy Krt7 immunoreactivity (5/48, 10.4%)." (PMID 29700411, 2018). "Immunohistochemical examination showed that the tumor cells were positive for cytokeratin 7 (CK7) and CDX-2 and negative for CK20." (PMID 29784024, 2018). "Three of the luminal markers KRT7, KRT19 and CD24 showed staining in the tumor transplants." (PMID 30550540, 2018). "Serous tumours, for the most part, show an opposite immunohistochemical pattern for those antigens and express ovarian epithelial tumour markers such as epithelial membrane antigen (EMA), CA-125 (cancer antigen 125), cytokeratin 7, CD15 (Leu-1), and Ber-EP4." (PMID 26197800, 2015). "Immunohistochemically, the tumor cells displayed positivity for keratin 20 and neuroendocrine markers, being negative for keratin 7 and S100 protein." (PMID 26607425, 2015). "Further immunohistochemistry showed the tumor was positive for cytokeratin 7 (CK7), CK20, villin, and ErbB2/HER2, but negative for gross cystic disease fluid protein-15 (GCDFP-15), ER, and PR." (PMID 25890325, 2015). "No keratin 7 positive-billiary channels either portal spaces were present in the tumor parenchyma; the reticulin framework examined with reticulin stain was intact." (PMID 26200629, 2015). "The tumor cells showed immunohistochemical positivity for AE1/AE3 and cytokeratin-7." (PMID 25000259, 2014). "The tumor cells are positive for cytokeratin 7, cytokeratin 20, and CA19-9, and they are negative for TTF-1, CA125, thrombomodulin, and mammaglobin." (PMID 24891967, 2014). "Immunohistochemical staining revealed that the tumor cells were reactive to cytokeratin-7 (CK-7), but were negative for CK-20." (PMID 23634311, 2013). "Immunohistochemically, the tumor cells were positive for cytokeratin 7 (CK7) and CA125 and negative for CK20 and CA19-9." (PMID 22747642, 2012). "By immunohistochemistry the tumor cells were cytokeratin 7 positive, cytokeratin 20 negative, and TTF-1 negative." (PMID 21559200, 2011). "Immunohistochemical analysis evidenced positive reactions with carcinoembryonic antigen (CEA) and cytokeratin 7 in almost all tumor cells, but negative reactions with PSA, CDX2, cytokeratin 20, CA-125 and androgen receptors." (PMID 19468449, 2009). "Both xenografted tumor lines had abundant expression of EMA, CEA and cytokeratin 7 (CK7)." (PMID 18088404, 2007). "An immunohistochemical panel showed the tissue to be cytokeratin 20 (CK-20) positive, cytokeratin 7 (CK-7) negative and villin negative, thus in keeping with a colorectal primary tumour." (PMID 17169149, 2006).
tumor (continued). "Western blotting analysis using KRT7 specific antibody, consistently showed a high level of KRT7 protein in Ta tumours and most T2-4 tumours compared to normal bladder biopsies." (PMID 16265353, 2005). "Immunohistochemical stains for KRT7 showed cytoplasmic protein expression specific for cancer cells in both Ta and T2-4 tumours, but absent in stromal cells." (PMID 16265353, 2005). "The tumor cells were non-immunoreactive for cytokeratin 7, cytokeratin 20, cocktail of cytokeratin AE1/AE3 – Cam 5.2, thyroid transcription factor (TTF-1), leucocyte common antigen (LCA, CD45), and MART-1." (PMID 15967023, 2005). "In triple‐negative breast cancer, the expression of KRT7 is abnormal and may be related to the invasion and metastasis of the tumor." (PMID 41488744, 2026). "An immunohistochemical feature of LOT is that the tumor expresses KRT7 but not KIT." (PMID 39980061, 2025). "The tumour cells in areas with pleomorphic polygonal epithelioid type cells spread in sheets without ductal morphology showed diffuse strong immunopositivity for EMA,p63 and p40 but immunonegative for Keratin 7, AR, GCDFP-15, Her2Neu, BerEp4, S100, SMA and calponin." (PMID 40822511, 2025). "The tumor cells were positive for CK34βE12, and negative for CK35βH11 and KRT7." (PMID 39138533, 2024). "Classic adenocarcinoma (ADC) markers were used, including cytokeratin 7 (CK7), thyroid transcription factor 1 (TTF-1), and napsin A. The results of H&E staining and IHC indicated that the LCOs retained the histopathological characteristics of the original tumor tissue or malignant pleural effusion." (PMID 38773241, 2024). "Submitted immunohistochemical stains were reviewed and show that the tumor cells in the biopsy specimen are positive for CK8/18 while negative for AE1/3, CD34, high molecular weight cytokeratin, CK20, RCC, desmin, myosin, smooth muscle actin (SMA), S100, Melan A, cytokeratin 7 (CK7), and GATA3." (PMID 39669804, 2024). "However, in their study, most reactive neoplasms had KRT7 staining of fewer than 25% of the cells, with none of the reactive neoplasm exhibiting KRT7 staining in more than 50% of the cells." (PMID 35406395, 2022). "Although the Krt7+ subpopulation did not appear to contribute to foregut tumor formation, it is still possible that there is an unknown subpopulation that may have significantly higher tumor susceptibility." (PMID 31110179, 2019). "Most historical studies have noted that immunoreactivity for KRT-7 in PCa typically occurs in rare individual cells within otherwise nonreactive tumor areas but, due to high cut-off values (5% or higher) in previous studies, most PCas have been reported as negative for KRT-7." (PMID 28446230, 2017). "The diagnosis of recurrent CRLM was corroborated by the immunohistochemistry that showed negative for cytokeratin 7 and positive for cytokeratin 20, indicating that the segment 4 tumor was CRLM but not intrahepatic cholangiocarcinoma that often develops in cirrhotic liver." (PMID 27234582, 2016). "By immunohistochemistry, the tumor cells were positive for vimentin and α-1-antichymotrypsin; negative for cytokeratin 7 (CK7), CK19, CK8/18, hepatocyte paraffin, mucin-1, cluster of differentiation 31 (CD31), CD34 and AFP; and the positive rate of Ki67 was 80%." (PMID 25120683, 2014). "Immunohistochemical staining showed the tumor cells were negative for PSA and NKX3.1 but positive for cytokeratin 7 (CK7)." (PMID 40821321, 2025). "Synaptophysin, chromogranin A, and CD56 are commonly used markers to identify NE differentiation and the non-NE markers include caudal-type homeobox 2 (CDX2), cytokeratin 7 (CK7), CK20, among others depending on the specific neoplasm." (PMID 41041158, 2025).
tumor (continued). "The tumor stained positive for thyroid transcription factor 1 (TTF1), cytokeratin 7 (CK7), and Napsin A, but negative for CDX-2, cytokeratin 20, and anaplastic lymphoma kinase (ALK), and presented a wild-type epidermal growth factor receptor (EGFR)." (PMID 39594178, 2024). "These included positive readings for ER (95%), PR (5%), cytokeratin-7 (CK-7), and GATA binding protein 3 (GATA-3), while P63 and KIT (CD117) were absent in the tumor cells and HER-2/neu score was zero." (PMID 39125514, 2024). "The tumor cells were immunoreactive for pan-keratin (AE1/AE3) and PAX8, but no reactivity with KRT7, CA9 and TFE3." (PMID 37415400, 2024). "Among the cytokeratins, strong and diffuse cytokeratin 8–18 expression was observed in all the neoplasms while in none of them significant staining of cytokeratin AE1/AE3 and cytokeratin 7 was found." (PMID 37938323, 2023). "Based on the Western blot results, we performed IHC analysis to study the expression of three proteins, KRT7, KRT19 and SRI, in GSD (non-tumor control), LN negative GBC and LN positive GBC." (PMID 37142981, 2023). "By contrast, livers that were tumor-free, be it from the sham cohort or the NASH cohort, exhibited little or no CA 19-9 or cytokeratin 7 staining." (PMID 33020436, 2020). "The tumor is negative for EMA, cytokeratin 7, cytokeratin 20, chromogranin A, synaptophysin, S-100 protein, HMB-45, desmin, SMA, EBV, CD117, DOG1, CD23, CD21, clusterin, MDM2, CD34, D240, and ERG." (PMID 31623602, 2019). "At immunohistochemistry, tumor cells were positive for CK20 (cytokeratin 20) and CDX2 (caudal type homeobox transcription factor 2), negative for CK7 (cytokeratin 7) and PSA (prostatic specific antigen)." (PMID 29110729, 2017). "Immunohistochemical examination of this tumor revealed positive staining for Cytokeratin 20, Mucin 2, and CDX2, although Cytokeratin 7 and Mucin 6 were negative." (PMID 28503335, 2017). "A histological examination of the resected S6 tumor revealed adenocarcinoma and was confirmed to be CRLM but not intrahepatic cholangiocarcinoma with negative cytokeratin 7 and positive cytokeratin 20 in immunohistochemistry." (PMID 27234582, 2016). "Tumoral cells from both BxPC-3 CAM tumor and PDAC samples were strongly positive for cytokeratin-7 and -19, CEA and Ki67 but negative for cytokeratin-20 and CD56 (data not shown)." (PMID 24040391, 2013). "Immunostains showed that the tumor cells express cytokeratin, EMA, cytokeratin 7, smooth muscle actin, P63, CEA, and S100 and are negative for desmin, LCA, CD34, and CD20." (PMID 23008793, 2012). "PDACs express cytokeratin 7 (CK7); however, CK7 is not an unequivocal IHC marker of PDAC because it is also expressed in the epithelium of the extrahepatic bile duct, gallbladder and neoplasms originating in these tissues." (PMID 36008616, 2022). "Patient tumor specimens (non-responders=13; responders=9) obtained from a clinical trial NCT01218048 were subjected to multispectral VECTRA staining for epithelial cell marker cytokeratin 7 (CK7), EphB4, and ephrinB2." (PMID 35725568, 2022). "In conclusion the cytokeratin 7 and/or MUC5AC-positive metaplastic foci and the non-conventional growths may have a role in cancer histogenesis, while tumour cytokeratin 7 and non-cohesive histotype may also predict poor patient survival." (PMID 33963925, 2021).
tumor (continued). "However, they were negative for other tumor marker immunostains such as desmin, S100 Proteins, cytokeratin 20 (CK20), cytokeratin 7 (CK7), thyroid transcription factor 1 (TTF1) and tumor protein (P63) without any atypical cells." (PMID 25123111, 2014). "In contrast, KRT7 was expressed in all CSLC, but not in the tumor stroma." (PMID 24324581, 2013). "Immunohistochemistry of liver metastatic biopsies and PDX tumor showed lack of expression of typical PCa (e.g., AR, PSA, PSAP, ERG) or neuroendocrine markers (synaptophysin), compatible with double-negative CRPC, but was positive for nuclear β-catenin expression, keratin 7 and 34βE12." (PMID 38907236, 2024).
cancer (288 papers, 1996 to 2026). A tumor composed of atypical neoplastic, often pleomorphic cells that invade other tissues. "Studies indicate that KRT7 is associated with cancer cell behaviors such as proliferation, migration, and invasion." (PMID 40231256, 2025). "Seventy-five AoV cancers were analyzed for cytokeratin 7 (CK7), CK20, and causal-type homeobox transcription factor 2 (CDX2) expression by IHC staining." (PMID 38167037, 2024). "Elevated KRT7 expression has been associated with aggressive cancer phenotypes, including increased cell proliferation, migration, invasion, and epithelial-to-mesenchymal transition." (PMID 39095562, 2024). "Other important genes in this list downregulated by TOX2-shRNA, such as ITGB7, SLAMF1, CD244, DPYSL3, KRT80 and KRT7, have been implicated in cancer progression or drug resistance." (PMID 37032358, 2023). "This includes functionally relevant proteins associated with LN metastasis in cancer such as KRT7, KRT19, SRI, NPM1, Annexin A2 (ANXA2), Annexin A5 (ANXA5)." (PMID 37142981, 2023). "Keratin-7 (KRT7) overexpression has been associated with poor prognosis in several cancers and is described as a novel prostate progenitor marker in the mouse prostate." (PMID 35406395, 2022). "KRT7 is detected in many tissues and its overexpression in tumors was associated with disease progression in several cancer types." (PMID 35406395, 2022). "The first pathology report found the following results: Cytokeratin 7 (CK7) - positive within carcinoma cells in underlying lymphovascular spaces; CK20 - appeared negative within a few remaining neoplastic carcinoma cells; and GATA3 - weak positivity within neoplastic carcinoma cells." (PMID 40125201, 2025). "Based on the significant fold change in LN positive GBC in mass spectrometric data and literature survey for their functional relevance and association with LN metastasis in cancer, we selected four proteins namely KRT7, KRT19, SRI and NPM1 for verification using Western blot analysis." (PMID 37142981, 2023). "The up-regulation of KRT7 may be associated with several biological processes related to cancer progression, including increased cell migration, invasion, and metastasis." (PMID 37954148, 2023). "Keratin-7 overexpression has been associated with poor prognosis in several cancers." (PMID 35406395, 2022). "Importantly, high keratin-7 expression in benign peri-tumoral glands was correlated with shorter bone metastasis-free survival and increased risk of cancer-specific mortality." (PMID 35406395, 2022). "Therefore, the up-regulation of KRT7 expression in cancer cells may be a potential diagnostic and therapeutic target for the treatment of various cancers." (PMID 37954148, 2023). "Conversely, the mesenteric lesion had enriched expression of the keratin family genes (KRT7, KRT17) involved in cancer progression as well as metastasis signature associated gene CEACAM6." (PMID 40018643, 2025). "Keratin 7 (KRT7), a member of the keratin family, is abnormally expressed in various types of cancer and promotes metastasis." (PMID 41590789, 2025). "For instance, Cytokeratin 7-expressing cells serve as models for studying the early transition from normal epithelium to cancer cells, while PAX8-expressing cells contribute to understanding cancers originating from fallopian tube epithelium." (PMID 40034272, 2025). "The cancer cell immunophenotype was cytokeratin 7 (CK7) (+), cytokeratin 20 (CK20) (−), estrogen receptor (ER) (+), Wilms’ tumor gene 1 (WT1) (−)." (PMID 40150013, 2025). "Strikingly, KEGG analysis indicated that cancer‐related signal pathways were enriched in ALB+KRT7+ EPCs, such as Wnt signalling." (PMID 39834100, 2025). "Specifically, our results showed an upregulation of Cldn7, Krt7, Axl, Tnc, Itgav, Itgb3, and Vcam1 in EpCAMhigh and EpCAMlow cancer cells relative to levels in full epithelial cancer cells." (PMID 39075581, 2024).